SPRR2A (small proline rich protein 2A)
Diseases named in the same sentence as SPRR2A in open-access papers (continued):
Sharing a sentence is not in itself a finding about the gene and the disease.
tumor (7 papers, 2020 to 2025). "In contrast, in another study involving 127 OSCC samples and healthy tissue from adjacent oral areas, the authors found that reduced expression of both SPRR1A and SPRR2A in tumour tissues was associated with the occurrence of lymphatic metastasis." (PMID 40647632, 2025). "Our aim was to determine the concentration of SPRR1A and SPRR2A in tumours samples obtained from 61 patients with HNSCC (OSCC, OPSCC, LSCC, HPSCC, NCSCC, and SSCC)." (PMID 40647632, 2025). "There was a moderate positive correlation of the SPRR2A protein in the tumour with the number of years a patient smoked (0.3557; p = 0.0121)." (PMID 40647632, 2025). "We speculate that the levels of SPRR1A and SPRR2A proteins in tumour samples will be significantly correlated with the following factors, such as selected demographic factors, smoking habit, alcohol consumption, and p16/HPV status." (PMID 40647632, 2025). "Also, we found a statistically significant difference between the SPRR1A and SPRR2A levels in tumour and margin samples obtained from patients that either abstain and occasionally or regularly consume alcohol." (PMID 40647632, 2025). "Furthermore, we found in tumour and margin samples from patients with concomitant diseases an association between SPRR1A and SPRR2A levels." (PMID 40647632, 2025). "Furthermore, for SPRR2A, we observed similar correlations in the tumour and margin samples." (PMID 40647632, 2025). "Therefore, the results of comparing SPRR1A and SPRR2A levels between tumour and margin samples may not fully reflect the true picture of molecular changes associated with tumour transformation." (PMID 40647632, 2025). "Therefore, the expression of the studied SPRR1A and SPRR2A in the margin tissue may differ from their levels in healthy tissue, which may lead to under- or overestimation of the expression differences between the tumour and the margin." (PMID 40647632, 2025). "Together, these data suggest that SPRR2A/2D are regulated by the RBM38-p73 axis and contributes to p73-mediate tumor suppression and inflammatory response." (PMID 34204113, 2021). "We found that the combined detection of SPRR2A and CEA resulted in a significantly better AUC than those of the individual tumor markers." (PMID 32908616, 2020). "To this end, we identified small proline-rich protein 2A and 2D (SPRR2A and SPRR2D) as novel targets of p73, which may contribute to inflammation and tumor suppression regulated by the RBM38-p73 axis." (PMID 34204113, 2021). "Interestingly, although OS is a tumor of mesenchymal origin, upregulated genes in MG-OKS cells included epithelial-related genes, such as small proline-rich protein 2A (SPRR2A), SPRR1A, keratin 6A (KRT6A), and keratin 6B (KRT6B)." (PMID 33008481, 2020). "Thus, further studies are warranted to determine whether SPRR2A/2D expression mediated by the RBM38-p73 axis links chronic inflammation and tumor suppression." (PMID 34204113, 2021).
infection (5 papers, 2020 to 2025). The state of being infected such as from the introduction of a foreign agent such as serum, vaccine, antigenic substance or organism. "To test the Sprr1a−/−;Sprr2a−/− mice for susceptibility to infection, we inoculated the skin of wild-type and Sprr1a−/−;Sprr2a−/− mice with 1 × 106 CFU of a bioluminescent strain of MRSA by topical application." (PMID 35234613, 2022). "Besides, SPRR2A is dominantly overexpressed under inflammation, stress, and infection statuses to protect barrier epithelial cells of the skin, lung, and intestine." (PMID 34934042, 2021).
bacterial infections (1 paper, 2025). "In a similar manner, small proline-rich protein 2A (SPRR2A) is activated in response to bacterial infections occurring in the stomach, lungs, and skin." (PMID 40696454, 2025).
SPRR2A also shares sentences with these, for which no sentence is quoted: atopic dermatitis (2 papers); cardiovascular diseases (1); cervical cancer (1); childhood onset asthma (1); chronic atrophic gastritis (1); chronic gastritis (1); diabetes (1); endocrine diseases (1); gastrointestinal disease (1); head and neck squamous cell carcinoma (1); hypohidrosis (1); ischemia (1); kidney diseases (1); liver cancer (1); lung carcinoma (1); sarcoma (1); squamous cell carcinoma (1).